ALB (albumin)
Diseases named in the same sentence as ALB in open-access papers (continued):
Sharing a sentence is not in itself a finding about the gene and the disease.
Hyperbilirubinemia (continued). "Out of 93 newborns who had cord albumin levels ≥3.75 g/dl, 18 (19.4%) developed hyperbilirubinemia after 72 hours of life, whereas of the 30 newborns who had cord albumin levels <3.75 g/dl, 15 (50%) developed hyperbilirubinemia after 72 hours of life." (PMID 37197121, 2023). "Hemodialysis has a poor removal effect on albumin bound bilirubin, and HP is the most effective method for treating hyperbilirubinemia." (PMID 38046623, 2023). "Very few studies use cord bilirubin, albumin, nucleated red blood cells (nRBC), and reticulocyte count as predictors for hyperbilirubinemia." (PMID 37197121, 2023). "Recently, a cord blood albumin level of less than 2.8 g/dL was shown to be significantly correlated with hyperbilirubinemia requiring early treatment, while cord blood albumin above 3.3 g/dL was associated with safe early discharge." (PMID 37892362, 2023). "Can reduction of Bf by supplementing albumin reduce the apoptosis of cerebellum cells in mice with hyperbilirubinemia?" (PMID 34527681, 2021). "UDCA and albumin were identified as favorable factors for recovery from extreme hyperbilirubinemia, whereas peak bilirubin grade, chronic liver disease, the number of dysfunctional organs, INR, and lactate were unfavorable factors." (PMID 34351969, 2021). "Among the most ordered chemistry assays for neonates are TBil and albumin, which inform neonatal hyperbilirubinemia diagnosis and subsequent treatment based on American Academy of Pediatrics guidelines for hyperbilirubinemia." (PMID 31906315, 2020). "The study evaluated the efficacy of phototherapy and 20% albumin infusion to reduce total serum bilirubin (TSB) in neonates with severe hyperbilirubinemia." (PMID 31547861, 2019). "ROC analysis revealed that CEI < 1.61, serum albumin ≤ 4.2 g/dl, and indirect bilirubin ≥ 0.5 mg/dl at baseline were the best cutoff values to predict the development of paritaprevir-induced hyperbilirubinemia." (PMID 29709031, 2018). "These links affecting bilirubin neurotoxicity included duration of hyperbilirubinemia, serum albumin level, blood-brain barrier integrity, gestational age and the like." (PMID 28072860, 2017). "Factors which increase UCBFREE, such as hypoalbuminemia, hyperbilirubinemia, and the presence of drugs which displace bilirubin from its binding sites on albumin, as well as BBB damage, have a clinical relevance in bilirubin-induced neurotoxicity." (PMID 28036021, 2016). "More importantly, it is acknowledged that acute hepatic decompensation would result in decreased albumin, hyperbilirubinemia and prolongation of the INR." (PMID 26383863, 2015). "The administration of sulfamethoxazole, which binds to albumin and competes with bilirubin, can increase the possibility of hyperbilirubinaemia and serious neurological complications such as kernicterus in neonates." (PMID 19830198, 2009). "Therefore, cord albumin reticulocyte count and nRBC were examined in this study to predict hyperbilirubinemia at 72 hours of life." (PMID 37197121, 2023). "Clinicians should consider measuring cord serum bilirubin, albumin, reticulocyte, and nRBC levels in neonates at risk of developing hyperbilirubinemia to identify those unlikely to need further assessment or intervention." (PMID 37197121, 2023). "Among the total bilirubin, not more than 0.01% constitutes circulating as free bilirubin (an unbound form), and an even ratio of cord blood bilirubin/cord blood albumin at birth has been reported to be a good indicator for the prediction of neonatal hyperbilirubinaemia." (PMID 37371159, 2023). "In order to develop acute central nervous system dysfunction and recapitulate hyperbilirubinemia more precisely, Gunn rats are often treated with hemolytic drugs or albumin–bilirubin displacers, such as sulphonamides or erythrocyte-lysing agents such as phenylhydrazine." (PMID 36078055, 2022).
Hyperbilirubinemia (continued). "Our study showed that pre-endoscopic serum albumin level, intrahepatic biliary obstruction, stage IV cancer, improvement of hyperbilirubinemia within 2 weeks after stenting, and receiving chemotherapy were independent risk factors for 90-day mortality in patients with pancreaticobiliary cancers." (PMID 36147905, 2022). "Additionally, a study conducted in India showed that hyperbilirubinemia was much more common in female than male neonates because albumin concentration differs between gender." (PMID 34479515, 2021). "Human serum albumin (HSA) or heme oxygenase-1 (HO-1) inhibitor SnPP (Tin protoporphyrin IX dichloride) was injected intraperitoneally into Ugt1−/− mice to establish a treatment model for endogenous hyperbilirubinemia." (PMID 34527681, 2021). "Moreover, patients with hyperbilirubinemia were found to have lower platelet counts, lower serum albumin, higher aspartate aminotransferase (AST), and higher alkaline phosphatase (ALP) levels than patients with normal bilirubin levels." (PMID 32563268, 2020). "Accordingly, it is reasonable to speculate that bilirubin is more likely bound to albumin in isolated hyperbilirubinemias than in cholestasis, and is therefore less likely to enter the skin in conditions like Dubin-Johnson." (PMID 30657454, 2019). "In another study, it was reported that 10% albumin had a protective effect against bilirubin toxicity and may be useful in children with severe hyperbilirubinemia." (PMID 31547861, 2019). "In particular, albumin infusion has been proposed to reduce the risk of kernicterus in acute phases of hyperbilirubinemia in newborns, but there is a lack of general consensus on the efficacy of this treatment." (PMID 28036021, 2016). "In conclusion, the results presented here supports the potential use of albumin infusions in severe acute neonatal hyperbilirubinemia and in Crigler-Najjar patients, to limit/avoid bilirubin neurotoxicity in situations in which ET may be required." (PMID 26541892, 2015). "Fourth, the equation may not be valid in situations where the BCP method may underestimate albumin concentration, namely in the presence of hyperbilirubinemia or in patients receiving dialysis due to the presence of an endogenous ligand." (PMID 19038049, 2008). "This key distinction explains the unexpected hyperbilirubinemia and dialyzer discoloration observed in this case, as standard dialysis membranes struggle to manage the complex interplay between elevated bilirubin and drug-albumin complexes, leading to membrane overload." (PMID 40777665, 2025). "Notably, the administration of albumin or by pharmacological inhibition of indirect bilirubin production in a genetic model of hyperbilirubinemia could improve neurodevelopment and reduce apoptosis of cerebral cells remarkably." (PMID 38020137, 2023). "In contrast, 80.6% of newborns with cord albumin levels of ≥3.75 mg/dL did not experience hyperbilirubinemia (>12 mg/dl) after 72 hours of life, indicating that high cord albumin levels may be associated with low bilirubin levels." (PMID 37197121, 2023). "Additionally, hyperbilirubinemia might persist despite resolution of biliary obstruction since conjugated bilirubin binds covalently to albumin and delays the clearance of bilirubin." (PMID 32852140, 2020). "The patients with relative hyperbilirubinemia were younger (P < 0.001), more frequently of the male sex (P < 0.001), and had higher levels of baseline laboratory parameters, including calcium (P < 0.001), albumin (P < 0.001), AST (P = 0.001), and ALT (P = 0.001), than those of the control group." (PMID 28225832, 2017). "Therefore, in this experimental setting, albumin infusion was not sufficient to prevent increased bioluminescence associated with hyperbilirubinemia." (PMID 28036021, 2016).
Hyperbilirubinemia (continued). "However, since the BCP method may underestimate albumin in patients on hemodialysis and with conjugated hyperbilirubinemia, the impact of different albumin assay methods and the inter-laboratory variability of 5vMELD should be investigated." (PMID 23349678, 2013). "Moderate post-hepatectomy liver insufficiency (Clavien-Dindo grade 1–2) developed in two patients, characterized by hyperbilirubinemia, increased INR, and decreased albumin levels." (PMID 39906731, 2024). "Our study showed that the high albumin concentration and use of UDCA were correlated with recovery from extreme hyperbilirubinemia." (PMID 34351969, 2021). "This study aimed to investigate the association between serum high-sensitivity cardiac troponin I (hs-cTnI) concentrations, platelet counts, and the severity of neonatal hyperbilirubinemia (NHB), as well as their correlation with the total bilirubin/albumin (B/A) ratio." (PMID 40886366, 2025). "Previous studies reported that the involvement of additional parameters besides bilirubin level, such as albumin level or DAT in cord blood, could provide better predictivity for neonatal hyperbilirubinemia." (PMID 40388773, 2025). "Disorders associated with impaired binding of bilirubin to albumin may result in neurological injury in premature infants (<37 weeks’ gestational age) with decreased bilirubin levels, leading to acute bilirubin encephalopathy in these infants without marked hyperbilirubinemia." (PMID 37371159, 2023). "We wanted to examine whether and to what extent albumin administration, possibly reducing the UCBFREE levels, may modify the pattern of cell proliferation observed in MITO-Luc mice subjected to hyperbilirubinemia." (PMID 28036021, 2016). "In addition, severe hyperbilirubinemia may induce BBB endothelial disruption, possibly exposing the neurons to both UCBFREE and albumin-bound UCB." (PMID 28036021, 2016). "No dogs developed a low albumin concentration in combination with increases in ALT or ALP activity, and no dogs developed hyperbilirubinemia with chronic dosing of zonisamide." (PMID 35238072, 2022).
hip fracture (67 papers, 2011 to 2026). Traumatic or pathological injury to the hip in which the continuity of either the femoral head, femoral neck, intertrochanteric or subtrochanteric regions is broken. "Univariate analysis showed that female gender, age, EF, FAC score, Cr, Na, AST, and albumin were significantly associated with hip fracture." (PMID 40781195, 2025). "Lower admission albumin levels have been independently associated with higher 30-day readmission rates in elderly hip fracture patients, highlighting the importance of maintaining adequate protein levels for optimal recovery." (PMID 40837358, 2025). "Many blood indicators have been demonstrated to be significantly associated with the mortality risk in hip fracture patients, such as hemoglobin, lymphocyte count, neutrophil count, and albumin level." (PMID 41393124, 2025). "All these factors likely contribute to the higher readmission risk seen with lower admission albumin levels in our elderly hip fracture cohort." (PMID 38528491, 2024). "Lower levels of serum albumin were significantly associated with greater length of stay and in-hospital mortality in institutionalized patients with hip fracture." (PMID 38567247, 2024). "Recent years have witnessed an increasing utilization of serum albumin levels in hip fracture patients, demonstrating their association with perioperative complications and long-term postoperative mortality." (PMID 39076765, 2024). "Lower admission albumin levels were independently associated with higher 30-day readmission rates in elderly hip fracture patients." (PMID 38528491, 2024). "In conclusion, our study has identified several independent risk factors for preoperative CMVT in geriatric hip fracture patients, including the time from injury to admission, smoking history, serum albumin levels, and D-dimer levels." (PMID 37720507, 2023). "While individual associations of RDW and albumin with hip fracture mortality have been explored in prior studies, our research seeks to elucidate the combined effects and potential synergistic relationships between these biomarkers." (PMID 37701840, 2023). "Although the data is limited to elderly hip fracture patients, lower serum albumin levels are independently associated with lower MMSE scores." (PMID 33607942, 2021). "Albumin is a biomarker of undernutrition and is a risk factor for mortality in hip fracture patients." (PMID 28902873, 2017). "Almost half of the hip fracture patients had low serum albumin at the time of admission and it was independently associated with 2.5-fold greater odds of short-term mortality." (PMID 22248167, 2012). "A recent study from Canada of 583 hip fracture patients found an association between low serum albumin levels at admission and in-hospital mortality." (PMID 22248167, 2012). "Therefore, we investigated the associations among the phase angle, serum albumin level, skeletal muscle mass on admission, and functional recovery in patients with hip fractures." (PMID 41393560, 2025). "Moreover, an AUC of 0.711 for the albumin ROC curve, indicates the good predictive value of albumin levels as an independent biochemical marker to assess the risk of 30-day readmission in elderly hip fracture patients after discharge." (PMID 38528491, 2024). "In this study, a high incidence of abnormal postoperative laboratory test results and a substantial intervention rate after THA for hip fracture patients were noted in the included patients, and risk factors for blood transfusion and albumin supplementation were identified." (PMID 33170383, 2020). "However, serum albumin level was used for this retrospective study since those data were available; moreover, it has been noted as a risk factor for poor outcomes in hip fracture patients." (PMID 31852457, 2019).
hip fracture (continued). "Therefore, comprehensive nutritional assessment should be conducted in elderly patients with hip fracture, focusing attention on patients with albumin below 35 g/L, and preoperative albumin as a key measurement index to accurately assess the risk of postoperative SSD." (PMID 41488107, 2025). "This study evaluated the effect of branched-chain amino acid (BCAA) supplementation on serum albumin levels in hip fracture patients." (PMID 41375751, 2025). "Considering their accessibility and affordability in daily clinical practice, blood indicators have attracted increased attention as biomarkers of mortality among hip fracture patients, such as hemoglobin, lymphocyte, platelet, and albumin." (PMID 40041469, 2025). "Using prospectively collected data over a five-year period, we identify that admission albumin is an independent predictor of 30-day mortality following hip fracture." (PMID 40275223, 2025). "National hip fracture database (NHFD) data, including the NHFS, were linked with admission biomarkers: albumin, C-reactive protein (CRP), neutrophil-lymphocyte ratio (NLR) and monocyte-lymphocyte ratio (MLR)." (PMID 40275223, 2025). "Serum albumin (ALB) is the most commonly used serum marker in the clinic for assessing protein-energy malnutrition in hip fracture patients." (PMID 40020120, 2025). "Threshold analysis of Glucose to Albumin Ratio on Postoperative Pressure Ulcers in geriatric hip fracture patients." (PMID 41001126, 2025). "More recently, adverse outcomes for patients with preoperative low albumin were measured in studies from 2011 and 2014, concerning patients admitted for acute hip fracture." (PMID 38731106, 2024). "The findings from this study are anticipated to furnish healthcare practitioners with valuable insights into the management of hip fracture patients, specifically in terms of interventions targeting albumin levels and nutritional status." (PMID 38528491, 2024). "In a retrospective analysis involving 278 elderly hip fracture patients, Wang observed that decreased perioperative serum albumin levels and increased C-reactive protein (CRP) levels were associated with adverse postoperative events." (PMID 39536046, 2024). "The glucose to albumin ratio transformed into GAR was superior to any other biomarker in predicting postoperative UTIs in elderly hip fracture patients (AUC = 0.756, p < 0.001)." (PMID 39076765, 2024). "Previous studies have examined prognostic biomarkers in hip fracture patients, such as low albumin levels, lymphocyte counts, and chemotactic cytokine CXCL-8." (PMID 39769198, 2024). "Numerous studies evaluated the nutritional status of patients with hip fracture through serum albumin values." (PMID 39519455, 2024). "Similarly, the lower albumin level reflected the relatively poor nutritional status or the disrupted physiological balance of protein metabolism responsive of inflammation or trauma (hip fracture), both which can predispose patients to developing thromboembolic problems." (PMID 37507789, 2023). "In the field of hip fracture, future studies were needed to conduct the randomized controlled trial, showing the effect of albumin supplementation on preoperative DVT." (PMID 37620804, 2023). "Our study identified that time from injury to admission, smoking history, serum albumin levels, and D-dimer levels were independent risk factors for preoperative CMVT in geriatric hip fracture patients." (PMID 37720507, 2023). "Based on a retrospective analysis of 471 elderly hip fracture patients, the median preoperative albumin level in those who died was 29.5 g/dl (SD 6.22 g/dl) and 32.8 g/dl (SD 6.43 g/dl) in those who survived." (PMID 37701840, 2023). "High preoperative levels of serum CRP (>10 mg/dL) and low levels of serum albumin (<3 g/dL) are widely considered independent predictors of mortality after hip fracture in the elderly population." (PMID 37445579, 2023).